CTLA4 (cytotoxic T-lymphocyte associated protein 4)
Diseases named in the same sentence as CTLA4 in open-access papers (continued):
Sharing a sentence is not in itself a finding about the gene and the disease.
tumor (continued). "It has been shown that CTLA-4 blockade of Teff increased Th function, while CTLA-4 blockade of Treg decreased Treg suppressive function, and that both are necessary for the anti-tumor activity of therapeutic CTLA-4 antibodies." (PMID 27330811, 2016). "Thus, we speculated that CTLA-4 expressed by either ESCC tumor cells or infiltrating lymphocytes contributes to the profile of immunosuppression that is observed in ESCC patients based on its ability to impair the function and survival of activated tumor-specific T cells." (PMID 27050369, 2016). "In accordance with the findings from the mRNA sequencing data, TIM-3, LAG-3 and CTLA-4 were expressed at higher levels in both CD4 and CD8 T cells from PD-1 resistant as compared with untreated EGFR TL tumours by flow cytometry analysis." (PMID 26883990, 2016). "Combining immune checkpoint inhibitors such as anti-CTLA4 and anti-PD1 mAbs can have dramatic effects on anti-tumor immune responses, and result in significant improvements in clinical outcomes, compared with single antibody treatment." (PMID 26872334, 2016). "Because PD-L1 is upregulated on tumor cells following BRAF inhibition, and anti-PD-1 therapy is less toxic compared to anti-CTLA-4, combining BRAFV600E inhibitors with anti-PD-1 therapy seems promising." (PMID 27847783, 2016). "T cells from peripheral blood (PBL) and tumor were analyzed for the expression of OX40, PD-1 and CTLA-4 in 29 patients undergoing surgery." (PMID 27195113, 2016). "In animal models, CTLA-4 expression was necessary to the immunosuppressive function of Tregs, and conditional knockout of CTLA-4 in Tregs protected from tumor development." (PMID 31093342, 2016). "In combination with the checkpoint-blockade using anti-cytotoxic T-lymphocyte antigen-4 (CTLA4), the generated immunological responses will be able to attack remaining tumour cells in mice, useful in metastasis inhibition, and may potentially be applicable for various types of tumour models." (PMID 27767031, 2016). "Blockade of both PD-1 and CTLA-4 in those mice resulted in reversal of CD8+ TIL dysfunction and led to tumor rejection in two-thirds of mice." (PMID 28536377, 2016). "Treatment with anti-PD-1 and anti-CTLA-4 as single agents resulted in T-cell infiltration into tumors; when anti-PD-1 and anti-CTLA-4 were combined, even greater numbers of CD3+ T cells and PD-L1+ cells were found within the tumor mass." (PMID 27610613, 2016). "In addition, upregulated expression of the immune checkpoints cytotoxic T lymphocyte-associated antigen 4 (CTLA4), programmed cell-death-1 (PD-1), programmed cell-death ligand-1 (PD-L1), lymphocyte activation gene 3 (LAG3) and indoleamine 2,3-dioxygenase (IDO) was noted in MSI tumours [34•]." (PMID 27340376, 2016). "The PD-L1/PD-1 and CD80/CTLA-4 interactions inhibit CD8+ cytotoxic T-lymphocyte proliferation and survival and affect the function of tumour-infiltrating T cells, which suppress the immune system and cause peripheral immune tolerance in cancer patients." (PMID 27147225, 2016). "MVA-BN-HER2 immunotherapy plus CTLA-4 checkpoint blockade led to a marked increase in the proportion of functional, HER-2-specific CD8 cytotoxic T cells infiltrating into tumor tissue." (PMID 26961085, 2016). "Several trials are now recruiting to investigate the combination of two checkpoint blockade inhibitors (CTLA-4 and PD1/PDL1 blockade) or combination with small molecule inhibitors to overcome the immunosuppressive tumor microenvironment." (PMID 27141395, 2016). "In the present study, we evaluated the interesting approach for CTLA-4 enhancement on PSCA-specific immune responses and its anti-tumor effects in a mouse model." (PMID 27783810, 2016). "While circulating tumor-specific T cells exhibited normal effector function, TILs isolated from the tumor-draining lymph node (TDLN) showed a markedly exhausted phenotype, characterized by decreased IFNγ expression and upregulation of CTLA-4 and Lag-3." (PMID 27314056, 2016).
tumor (continued). "In summary, we demonstrated that combination therapy of α-CTLA-4 and α-PD-1 elicited stronger anti-tumour immune responses, potent MB49 tumour rejection, and induced protective immunity against re-challenge." (PMID 27498556, 2016). "For this reason, T-cell-based immunotherapy targeting CTLA4 and PD1 has been tested to unleash anti-tumor T-cell responses to various tumors." (PMID 27551523, 2016). "The increased expression of the CTLA-4 molecule found in the T cell compartment in CLL patients seems to be an unfavourable factor, because it specifically inhibits anti-tumour immunity in these patients." (PMID 26490985, 2016). "Tumors with mismatch repair deficiency also have a high expression of immune checkpoint ligands such as PD-L1, PD-1, CTLA-4, and LAG-3, which effectively counterbalance the active Th1 response and prevent tumor elimination." (PMID 26510455, 2015). "Flow cytometric analysis of tumor-infiltrating lymphocytes revealed that administration of IFN-γ and IL-2 downregulated the expression of CTLA-4 on CD3+ CD8+ TILs compared to control groups on day 14 post-transfer." (PMID 26107883, 2015). "Co-culture of tumor cells and splenocytes derived from mice treated with LRT combined with anti-CTLA4 mAb displayed more cytotoxic T cells and more frequent cytolytic target cells, compared with those from the LRT alone group." (PMID 25980578, 2015). "We treated mice with anti-CTLA4 or PBS, surgically removed one of the tumours 7 days after treatment administration, at which time regressor and progressor tumours are macroscopically identical." (PMID 26193793, 2015). "Strikingly, α-CTLA-4/α-PD-L1 mAb treated mice that had controlled initial K7M2 tumors, were completely immune to challenge with additional K7M2 cells, and remained tumor free for an additional 80 days when they were euthanized to evaluate immune memory." (PMID 25992292, 2015). "Quantification of tumor-infiltrating T cells by flow cytometry showed that the percentages of total T cells, and CD4+ and CD8+ T cells were higher in LRT followed by CTLA-4 blockade in both T1 and T2." (PMID 25980578, 2015). "The combination of anti-CTLA-4 antibody and ICOS activation, which was mediated by tumor vaccines engineered to express the ICOS ligand, enhanced anti-tumor response." (PMID 25859247, 2015). "Indeed, treatment with an activator of CD8+ T cells, Ipilimumab (anti-CTLA-4), together with an inhibitor of VEGF signaling (Bevacizumab) causes perivascular CD8+ cell accumulation, thus confirming the relevance of the vasculature for tumor-infiltration of cytotoxic T cells." (PMID 25885274, 2015). "An anti-CTLA-4 antibody would block such an inhibitory signal, thereby enhancing the interaction of CD28 with its ligand B7 on the tumor cell." (PMID 26579545, 2015). "Taken together, the growth delay of both primary tumors (T1) and secondary tumors (T2) was achieved in mice whose primary tumor was treated with LRT, while the addition of CTLA-4 antibody enhanced the radiation-induced antitumor effect." (PMID 25980578, 2015). "CTLA-4 also mediates direct inhibitory effects on the MHC-TCR pathway and suppresses antitumor immune activities in the tumor microenvironment." (PMID 26579545, 2015). "The induction of CTLA-4 expression on CD8+ T cells and PD-L1 expression on tumor cells suggests the onset of acquired resistance to effective anti-tumor immune responses." (PMID 26500653, 2015). "Whereas CTLA-4 is well known to dampen effector T cell function, regulate homeostatic lymphoproliferation and induce tolerance, its effect on adoptively transferred tumor-targeted human T cells, including T cells that are costimulated through a second generation CAR, is presently unknown." (PMID 26110267, 2015). "Both spleen and bone marrow-derived CD4 and CD8 T cells showed a significant increase in tumor-specific IFN-γ producing cells when mice were treated with anti-PD-L1 in combination with anti-TIM-3, or anti-LAG-3 or anti-CTLA4 as compared to anti-PD-L1 alone." (PMID 25614821, 2015).
tumor (continued). "CTLA-4 blockade increased immune cell infiltration (including CD8+ T cells and NK cells) in the tumor and IL-2 reduced the proportion of highly differentiated/exhausted tumor-infiltrating NK cells." (PMID 25992289, 2015). "Pointing to a concurrent cis mechanism of action, experimental evidence in CTLA-4−/− mice carrying human CTLA-4 suggested that anti-CTLA-4 mAb would need to bind to both Teff and Treg cells to produce full tumor protection." (PMID 25859247, 2015). "In animal studies, combination of immune check point inhibitors such as combining anti-CTLA4 and anti-PD1 antibodies enhanced effectory T-cell infiltration in tumor lesions resulting in decreased regulatory T-cell density." (PMID 26060497, 2015). "To determine if NOS2 plays a major role in the response to CTLA-4 blockade, we treated mice with established AB1-HA tumours with anti-CTLA-4 in combination with competitive NOS2 inhibitor L-NG-nitroarginine." (PMID 26193793, 2015). "Ipililumab, an mAb directed against CTLA-4, was the first therapy to procure survival benefits for patients with metastatic melanoma, providing proof-of-concept that disrupting checkpoint molecules could alone reverse tumor immunoresistance and lead to immune-mediated tumor eradication." (PMID 26217588, 2015). "In another study that utilized the same model, a combination of anti-CTLA-4 and anti-4-1BB-enhanced CD8 T-cell mediated anti-tumor response and significantly reduced liver metastasis when compared with treatment utilizing either antibody alone." (PMID 26510455, 2015). "The expression of PD-1, CTLA-4, and LAG-3 in OVA tetramer-positive CD8 lymphocytes within the tumor on day 21 was analyzed using flow cytometry." (PMID 25354479, 2015). "Co-administration of anti-PD-1 antibodies and anti-CTLA-4 antibodies reversed the TIL dysfunction and induced tumor regression in 50% of the mice relative to 25% with either agent as a monotherapy." (PMID 25806106, 2015). "In particular, CTLA-4 blockade increased the relative proportion of CD8+ T cells and NK cells among tumor-infiltrating immune cells." (PMID 25992289, 2015). "Checkpoint inhibitors (anti-CTLA4, anti-PD-1/anti-PD-L1, anti-LAG-3, anti-BTLA), as well as agonists of CD40 or TLR, are also known to improve anti-tumor T cell survival." (PMID 25325015, 2014). "However, results have been promising with one study showing that replication competent VSV in combination with anti-CTLA-4 mAb resulted in the elimination of macroscopic tumor implants in the majority of test animals, an outcome that could not be achieved by either treatment alone." (PMID 24605114, 2014). "Single blockade of the immune-inhibitory pathways CTLA-4, PD-1/PD-L1, or IDO has been shown to have modest yet significant impact on tumor growth kinetics and to improve tumor-specific immune responses in various mouse models in vivo." (PMID 24829760, 2014). "By targeting CTLA-4, ipilimumab blocks interaction with its ligands, CD80/CD86, leading to increases in T-cell mediated anti-tumor responses." (PMID 25101247, 2014). "In animal studies, ICOS was found to be necessary for optimal anti-tumor responses with anti-CTLA-4 and ICOS was shown to mediate PI3K-signaling to increase T-bet expression in the setting of anti-CTLA-4 therapy." (PMID 24883190, 2014). "In conclusion, we have developed 64Cu-DOTA-anti-CTLA-4 mAb and evaluated its potential as a new radiotracer for the noninvasive evaluation of CTLA-4 expression in tumor." (PMID 25365349, 2014). "Consistently, priming of T cells to a tumor-specific CD8 T cell epitope in mice treated with radiotherapy and anti-CTLA-4 or anti-CD137 was markedly enhanced in iNKT−/− compared to WT mice." (PMID 25349699, 2014). "Indeed, targeting ICOS may lead to improved anti-tumor responses with anti-CTLA-4 therapy." (PMID 24883190, 2014). "In a follow-up study, CTLA-4 blockade prevented and/or slowed the outgrowth of subcutaneous TRAMP-C2 tumours, which spontaneously metastasise to the regional lymph nodes." (PMID 25276838, 2014).
tumor (continued). "In our experiments, the full-length form of CTLA-4 (amplicon length: 920 bp), which is a representative immunosuppressive form of CTLA-4, was expressed in the CT26 tumor tissues." (PMID 25365349, 2014). "For exploring CTLA4-FasL efficacy in-vivo, NUDE mice were injected (sc) with JY cells and followed daily for tumor growth." (PMID 25227919, 2014). "Among the antibodies tested, an anti-CTLA-4 antibody significantly increased the anti-tumor efficacy of irradiation, with the TGD extended from 13.1±2.3 (irradiation alone group) to 19.5±2.9 (anti-CTLA-4 antibody plus irradiation group) days (p<0.005)." (PMID 24686897, 2014). "Due to its role in maintaining tolerance, blocking CTLA-4 interaction with CD80 and CD86 was postulated to promote anti-tumor immunity." (PMID 23450201, 2013). "The majority of tumor-derived Tim-3+ CD4 T cells exhibited an impaired capacity to produce IFN-γ and IL-2, but expressed higher levels of CD25, Foxp3, CTLA-4 and GITR than their Tim-3− CD4 T cell counterparts." (PMID 23526963, 2013). "When the immunotherapeutic efficacy of PC61 and anti-CTLA-4 treatment in conjunction with E6-RHDV-VLP-PADRE immunization was compared, both treatments were comparable in their ability to reduce tumour area (M-W U test; ns) and enhance survival (M-C test; ns)." (PMID 23799135, 2013). "The E6-RHDV-VLP-PADRE was administered therapeutically for the treatment of a pre-existing TC-1 tumour and was delivered with antibodies either to deplete regulatory T cells (anti-CD25) or to block T cell suppression mediated through CTLA-4." (PMID 23799135, 2013). "In contrast, repeated administration of a combination of mAbs to CD137 plus PD-1 doubles tumor-free survival of mice with established ID8 carcinoma, and addition of a mAb to CTLA4 further increases it." (PMID 24367702, 2013). "Based on published evidence indicating a therapeutic potentials in several tumor models we tested mAbs to CD137, CD40, CTLA-4, PD-1, TIM-3 and LAG-3, as single agents and in combinations." (PMID 24367702, 2013). "Certain iRs (PD1, CTLA-4, TIM-3, LAG-3) can be particularly highly expressed in the tumor microenvironment (TILN), but there was high variability." (PMID 24391639, 2013). "In the tumor-bearing prostate gland itself, more than half of the specific CD8 T cells expressed CTLA-4." (PMID 23557194, 2013). "The percentage of tumor-infiltrating Foxp3+CD4+ T cells was significantly decreased in tumors treated with gemcitabine, anti-CTLA-4 or the combination treatment, a finding consistent with previously published data." (PMID 23626745, 2013). "We next sought to evaluate the impact of anti-CTLA-4 and GVAX combination immunotherapy on tumor antigen-specific CD4 T cell numbers and function." (PMID 23557194, 2013). "Recently, we reported two other fusion proteins, CTLA-4•FasL and CD40•FasL, with cytotoxic activity against tumor cells." (PMID 24130833, 2013). "CTLA-4 blockade and GVAX treatment resulted in an increase in the ratio of tumor antigen-specific CD4 and CD8 Teffs to Tregs." (PMID 23557194, 2013). "In the presence of the tumor's microenvironment, the CTLA-4 molecule is upregulated on the T cells with the help of TGF-beta, a suppressive cytokine secreted by the tumor cells." (PMID 23936819, 2013). "Three days after tumor cell injection, mice were treated with either combination therapy (GVAX + anti-CTLA-4), or each treatment alone." (PMID 23557194, 2013). "Expression of CTLA-4 on CD8 HA-specific T cells in prostate and prostate draining lymph nodes significantly increased between days 4 and 7 in tumor bearing mice." (PMID 23557194, 2013). "The expression of several lymphocyte signaling molecules, including CTLA4, LAT, PDCD1, and ZAP70, was maintained in the transition from human tumor to CX, and was particularly prominent in the CXs derived from D61540." (PMID 24278200, 2013).
tumor (continued). "Combined treatment of anti-CTLA4, PD-1, TIM-3 and CD40 mAbs also suppressed tumor growth but was less efficacious with mean survival time 49 days." (PMID 24367702, 2013). "The increased CTLA-4 expression was observed in the majority of NSCLC patients, and it was significantly correlated with TT genotype (−318C/T) and with tumor size (T2 versus T3 + T4)." (PMID 23936819, 2013). "Elevated levels of Lag-3 and CTLA-4 were found in PD1+ CD4 T cells from HIV-infected patients and in tumor-derived NY-ESO-1-specific CD8 T cells." (PMID 22548114, 2012). "Tumor-specific T-cells from TILN were lower in KLRG-1 expression but higher in TIM-3, LAG-3 and CTLA-4 expression as compared to cells with the same specificity in blood." (PMID 22347406, 2012). "It has been reported that the anti-CTLA-4 monoclonal antibody ipilumumab blocks the activation of immunosuppressive CTLA-4, and thus induces tumor regression." (PMID 23133541, 2012). "The mean fluorescence intensity (MFI) showed that Treg had more CTLA-4 per cell than conventional CD4+ T cells, both in the tumor and in the unaffected tissue." (PMID 22319577, 2012). "A recent study identified circulating and tumor infiltrating CD28+ CD8+ Tregs with a CD25+, FOXP3+, CTLA-4+, GITR+, CCR4+, TGF-β+ and CD127low/neg phenotype." (PMID 24212779, 2011). "One such mechanism is represented by tumor-induced overexpression of CD80 (B7-1) on the surface of MDSCs, to which the inhibitory CTLA-4 (CD152) molecule expressed on CD4+CD25+ T cells binds with high affinity." (PMID 22190971, 2011). "While CTLA-4 blockade did increase IFN-γ production from CD8 T-cells in the vaccine and tumor draining lymph nodes, α4-1BB evoked much stronger increases in IFN-γ, TNF-α, and IL-6 production." (PMID 21559358, 2011). "The addition of CTLA-4 blockade further increased IFN-γ production from CD4+ effector T-cells in the vaccine draining node and the tumor." (PMID 21559358, 2011). "In summary, when the anti-CTLA4 gene was delivered using the HSC-based approach, it stimulated tumor growth in both tumor models." (PMID 21779410, 2011). "In a pilot phase I trial of the anti-CTLA4 antibody tremelimumab plus a MART-1 peptide-pulsed DC vaccine, objective and durable tumor responses were seen at higher level than what would have been expected with either approach alone." (PMID 20875102, 2010). "Antibody-mediated blockade of CTLA-4 signaling can augment antigen-specific CD8 T cell responses in a CD4-independent manner, promoting anti-tumor and autoimmune effects." (PMID 19247441, 2009). "For CTLA-4 blockade, B. fragilis can induce Th1-weighted systemic immunity, as shown in germ-free or antibiotic-treated mice, anti-CTLA-4 therapy had no anti-tumor effect until B. fragilis bolstering Il-12 production was introduced." (PMID 41486167, 2026). "For instance, partial non-response to anti-CTLA-4 therapy stems from collagen deposition-induced reductions in T cells tumor infiltration." (PMID 41362727, 2026). "We investigated the HPA immunohistochemistry and DepMap CRISPR screenings to confirm the tumor-intrinsic essentiality of PLK1 and AURKA, while utilizing the TISCH single-cell dataset to validate the microenvironmental specificity of CTLA4 (T-cells) and PPARG (CAFs/Macrophages)." (PMID 41596281, 2026). "Biodistribution experiments of [211At]1 and therapeutic experiments of [211At]1 with or without anti-PD-1 or anti-CTLA-4 antibody were conducted in Colon-26 tumor-bearing BALB/c mice." (PMID 40768094, 2026). "A high HRS was associated with immune escape by reshaping the T-cell-infiltrated tumor microenvironment (TME), and showed strong positive correlations with cancer-immunity cycle activity, PD-L1/CTLA-4 immune checkpoint expression, and T-cell inflammation scores." (PMID 41584042, 2026).